PPP2R5D (protein phosphatase 2 regulatory subunit B'delta)
Diseases named in the same sentence as PPP2R5D in open-access papers (continued):
Sharing a sentence is not in itself a finding about the gene and the disease.
neurodevelopmental disorder (11 papers, 2020 to 2025). A behavioral and cognitive disorder with onset during the developmental period that involves impaired or aberrant development of intellectual, motor, or social functions. "Protein phosphatase two regulatory subunit B’ delta (PPP2R5D)- related neurodevelopmental disorder is caused by pathogenic variants in the PPP2R5D gene which commonly results from de novo missense variants." (PMID 38326877, 2024). "At present, the neurodevelopmental disorder caused by PPP2R5D gene variants is defined as the Houge–Janssens syndrome 1 (HJS1) in Online Mendelian Inheritance in Man (OMIM:616355)." (PMID 39201832, 2024). "As of 2023, there were 103 people with PPP2R5D related neurodevelopmental disorder published, with 16 different genetic variants." (PMID 38326877, 2024). "Protein phosphatase 2 regulatory subunit B’ Delta (PPP2R5D)-related neurodevelopmental disorder is a rare genetic condition caused by pathogenic variants in the PPP2R5D gene." (PMID 38326877, 2024). "Due to the prevalence of neurodevelopmental disorders (NDD) in PPP2R5D-variant affected children, we also investigated which genes corresponding to proteins with significantly altered phosphorylation sites are associated explicitly with NDD." (PMID 33482199, 2021). "All patients were diagnosed as having PPP2R5D-related ID and neurodevelopmental disorder after the identification of a heterozygous pathogenic variant in PPP2R5D on molecular genetic testing established in a proband." (PMID 32074998, 2020). "Knowledge of the natural history of PPP2R5D related neurodevelopmental disorder will lead to improved standard of care treatments as well as serve as a baseline foundation for future clinical trials." (PMID 38326877, 2024). "The GMFM-66 was also able to differentiate between functional levels in PPP2R5D related neurodevelopmental disorder demonstrating discriminant validity." (PMID 38326877, 2024). "The GMFM is a valid measure for characterizing motor function in individuals with PPP2R5D related neurodevelopmental disorder." (PMID 38326877, 2024). "Case presentation: We report the first PPP2R5D-related neurodevelopmental disorder case from Sardinia, a child with transient hypoglycaemia, facial dysmorphisms, and multiple haemangiomas." (PMID 39728742, 2024). "The aim of this study was to validate the gross motor function measure (GMFM) in children and adults with PPP2R5D-related neurodevelopmental disorder in order to better characterize the disorder." (PMID 38326877, 2024). "The GMFM is a valid tool to evaluate and characterize motor function in children and adults with PPP2R5D related neurodevelopmental disorder." (PMID 38326877, 2024). "This suggests that the development of future therapies aimed at specifically targeting PPP2R5D-dependent effects on AKT/mTOR signaling in PPP2R5D-related neurodevelopmental disorder should be mindful of potential salutary effects." (PMID 33482199, 2021). "Because PPP2R5D-related clinical signs can overlap with clinical features of other neurodevelopmental disorders, a differential diagnosis is achieved by combining MRI data along with genetic testing of the proband for pathogenic PPP2R5D variants." (PMID 32074998, 2020). "Ppp2r5d, encoding B56δ (a delta isoform of the regulatory subunit B56 subfamily of PP2A) has been shown to be involved in neurodevelopment and tumorigenesis, and its mutant leads to mental retardation and neurodevelopmental disorder." (PMID 39200351, 2024). "With future clinical trials, the GMFM could serve useful as a motor function endpoint in PPP2R5D related neurodevelopmental disorder and additionally as part of clinical management for this and other genetically determined neurodevelopmental disorders." (PMID 38326877, 2024).
neurodevelopmental disorder (continued). "Although the GMFM has not yet been validated for use in individuals with this rare genetic disease, many of the impairments seen in individuals diagnosed with PPP2R5D related neurodevelopmental disorder closely resemble those with SMA and DS, specifically hypotonia and developmental delay." (PMID 38326877, 2024). "Specifically, PP2A-related neurodevelopmental disorders are characterized by mutations in PPP2R1A (Aα), PPP2CA (Cα), PPP2R2C (B55γ), PPP2R5B (B56β), PPP2R5C (B56γ), and PPP2R5D (B56δ), with most patients and mutations, so far, found in PPP2R5D." (PMID 36313552, 2022). "However, no other variants were tested, and the downstream molecular effects need to be further assessed to better understand the aetiology of PPP2R5D-related neurodevelopmental disorders." (PMID 36313552, 2022).
tumor (8 papers, 2013 to 2023). "Ppp2r5d-deficient HCCs stained positively for c-MYC, consistent with increased AKT activation in pre-malignant and tumor tissues of Ppp2r5d-deficient mice." (PMID 37627221, 2023). "We also observed that Ppp2r5d is upregulated in tumors from wildtype and heterozygous mice, and that loss of Ppp2r5d alters specific oncogenes and signaling pathways in pre-tumor and tumor tissues." (PMID 37627221, 2023). "These mutated genes include serum response factor (SRF) and PPP2R5D, which were detected in individual tumor samples." (PMID 30093687, 2018). "Notably, increased AKT activation was already observed in the non-tumor tissue and was further maintained in the tumors, further substantiating a predisposing role for increased AKT activity in the earlier tumor onset seen in Ppp2r5d KO as compared to HE and WT mice." (PMID 37627221, 2023). "In the current study, we have applied the principles of DEN-induced hepatocarcinogenesis to Ppp2r5d KO mice to expedite tumor formation and further study the tumor-suppressive role of PP2A-B56δ in mouse liver." (PMID 37627221, 2023). "Given the importance of PPP2R5D in regulating cell physiology, different diseases, and being a tumor-suppressive Ser/Thr protein phosphatase, it will be interesting to explore its role in HCV-related HCC." (PMID 35836293, 2022). "Ppp2r5d deletion (heterozygous and homozygous) accelerated HCC development, corroborating its tumor-suppressive function in liver and suggesting Ppp2r5d may be haploinsufficient." (PMID 37627221, 2023). "Moreover, YAP Ser127 phosphorylation levels were significantly lower in HE and HO mice, as compared to WT mice, both in the non-tumor and the tumor tissues, thus corroborating an unexpected role for Ppp2r5d in suppressing YAP activation." (PMID 37627221, 2023). "For this purpose, 2-week-old wildtype Ppp2r5d +/+ (WT), heterozygous Ppp2r5d +/− (HE), and homozygous Ppp2r5d −/− (HO) mice were injected with DEN, and tumor development was followed up to 11 months post-DEN injection." (PMID 37627221, 2023). "Our findings may imply that Ppp2r5d depletion could result in increased c-MYC activation through AKT activation, thus contributing to increased tumorigenesis and tumor progression." (PMID 37627221, 2023). "Our data thus further confirm the tumor-suppressive role of PP2A-B56δ in the liver, and underscore for the first time that Ppp2r5d may actually exhibit haploinsufficiency for hepatocarcinogenesis." (PMID 37627221, 2023). "The complete or partial Ppp2r5d depletion further promoted YAP activation, whereas complete Ppp2r5d depletion resulted in the upregulation of AKT activity already in pre-malignant livers, which likely contributed to the increased tumor onset seen in HO versus HE Ppp2r5d KO mice." (PMID 37627221, 2023). "Interestingly, while verifying Ppp2r5d depletion in livers from WT, HE, and HO mice, we unexpectedly found altered expression of B56δ specifically in the tumor tissues as opposed to the non-tumoral surrounding tissues in both WT and HE mice." (PMID 37627221, 2023). "Finally, we observed an upregulation of Ppp2r5d in tumors from wildtype and heterozygous mice, revealing a tumor-specific control mechanism of Ppp2r5d expression, and suggestive of the involvement of Ppp2r5d in a negative feedback regulation restricting tumor growth." (PMID 37627221, 2023). "In addition, we show increased expression of Ppp2r5d in DEN-induced WT and HE tumors, but not in DEN-treated pre-malignant WT or HE livers, suggestive of the involvement of Ppp2r5d in a negative feedback regulation, downstream of a tumor-specific, oncogenic factor." (PMID 37627221, 2023).
neurological disease (2 papers, 2023 to 2025). "Moreover, supporting RFX7’s potential role in neuronal development and neurological disorders, we identified regulators of neuronal processes among the novel RFX7 targets, such as JUN, SYNPO, PPP3CA, and PPP2R5D." (PMID 36864036, 2023).
infection (1 paper, 2022). The state of being infected such as from the introduction of a foreign agent such as serum, vaccine, antigenic substance or organism. "Infection experiment revealed that PPP2R5D-KO cells were hardly infected by HCV at day 7 post infection, when compared with WT Huh7.5 cells." (PMID 35836293, 2022).
PPP2R5D also shares sentences with these, for which no sentence is quoted: cancer (2 papers); cardiomyopathy (2); melanoma (2); myocardial infarction (2); Parkinsonism (2); 22q11.2 deletion syndrome (1); Alzheimer disease (1); autosomal dominant intellectual disability (1); Baraitser-Winter syndrome (1); bipolar disorder (1); breast carcinoma (1); colon adenocarcinoma (1); colon tumors (1); Cornelia de Lange syndrome (1); DOORS syndrome (1); Down syndrome (1); early infantile epileptic encephalopathy (1); glioblastoma (1); hepatitis C virus infection (1); left ventricular hypertrophy (1); liver (1); lung carcinoma (1); syndromic epilepsy (1); tauopathy (1); triple-negative breast carcinoma (1); ventricular dilatation (1).